CAPS (calcyphosine)
Description:
Calcium-binding protein. May play a role in cellular signaling events (Potential).
Synonyms: CAPS1; MGC126562
Tractability: Small molecule: it has a high-quality binding pocket. Antibody: its Gene Ontology location is reachable by antibodies, with high confidence.
Gene: Protein-coding gene on chromosome 19 (5,912,339 to 5,916,211, forward strand). Ensembl gene ENSG00000105519.
Subcellular location: Cytoplasm
Subcellular location (Human Protein Atlas): Cytosol; Plasma membrane
Gene Ontology:
Molecular function: calcium ion binding
Biological process: intracellular signal transduction
Cellular component: cytosol; vesicle; cytoplasm
Genetic constraint (gnomAD): Loss-of-function variants: 17 observed, 17.47 expected, observed/expected ratio (o/e) 0.97, 90% interval 0.67 to 1.46. The upper end of that interval is the gene's LOEUF score, 1.46, which puts it in group 6 of 6, group 1 being the genes least tolerant of losing a copy. Missense variants: 294 observed, 282.07 expected, observed/expected ratio (o/e) 1.04, 90% interval 0.95 to 1.15. Synonymous variants: 121 observed, 120.6 expected, observed/expected ratio (o/e) 1, 90% interval 0.87 to 1.17.
Homologues: Orthologues: chimpanzee CAPS (100% identical), macaque CAPS (97% identical), pig CAPS (87% identical), guinea pig CAPS (83% identical), dog CAPS (81% identical), Drosophila melanogaster TpnC41C (21% identical), Drosophila melanogaster TpnC47D (17% identical), Drosophila melanogaster TpnC73F (17% identical). Paralogues in human: CAPSL (52% identical), CAPS2 (32% identical), EFCAB6 (17% identical), PHF24 (16% identical), SPATA21 (8% identical).
Diseases named in the same sentence as CAPS in open-access papers:
CAPS is named in the same sentence as 48 diseases in open-access papers, as found by Europe PMC text mining. Sharing a sentence is not in itself a finding about the gene and the disease. The quoted sentences say what the papers report.
endometrial cancer (6 papers, 2011 to 2025). Primary or metastatic malignant neoplasm involving the endometrium (mucous membrane that lines the endometrial cavity). "Genes with the lowest tumor to normal methylation ratios include the chromosome 4 variant of the oncogenic promoting gene ubiquitin hydrolase DUB3 (19% decrease) and CAPS (oncogene implicated in endometrial cancer, 25% decrease)." (PMID 22174824, 2011). "Future work will therefore focus on in vivo modeling, genetic rescue experiments, and cross-dataset single-cell validation to further elucidate the regulatory mechanisms and translational implications of CAPS in endometrial carcinoma and other malignancies." (PMID 41383604, 2025). "The calcium-dependent activator protein for secretion (CAPS) has emerged as a protein of interest in tumor biology; however, its functional significance in endometrial carcinoma (EC) remains largely unexplored." (PMID 41383604, 2025). "In summary, CAPS represents a promising molecule of prognostic and therapeutic relevance in endometrial carcinoma." (PMID 41383604, 2025). "A third smaller, but distinctly separate, network of IL13, IL21, ANKAR, CAPS, and IGFALS was associated with Wnt and VEGF signaling, and are likely associated with environmental cues in high-grade endometrial cancer." (PMID 32471032, 2020). "EPCAM and CAPS were selected for further investigation based on their implication in the development of ovarian and endometrial cancer." (PMID 33384952, 2020). "One interesting example was CAPS, a protein related to low differentiation and worse survival of patients with endometrial cancer." (PMID 22415234, 2012). "Moreover, recent studies found higher CAPS levels in endometrial cancer compared to normal proliferative tissue." (PMID 25878567, 2015).
glioma (4 papers, 2022 to 2025). A benign or malignant brain and spinal cord tumor that arises from glial cells (astrocytes, oligodendrocytes, ependymal cells). "In gliomas, the interaction between CAPS and MYPT1, a crucial controller of protein phosphatase 1C, has been discovered, highlighting its significant role in cell cycle regulation." (PMID 39994841, 2025). "For example, CAPS has been shown to promote glioma progression by activating the Ca2+-ERK pathway and to facilitate tumor growth in gastric and lung cancers." (PMID 41383604, 2025). "Previous experimental evidence indicates that elevated CAPS expression enhances glioma cell proliferation in both in vitro and in vivo settings, suggesting a previously underestimated oncogenic function in glioma pathogenesis." (PMID 41423530, 2025). "CAPS is a calcium-binding protein related to cell proliferation and differentiation signals and associated with poor prognosis in CRC and gliomas and drug resistance in breast cancer, which is consistent with our results." (PMID 35968507, 2022). "Although CAPS overexpression has been reported in multiple cancer types—including ependymoma, endometrial, lung and colorectal, its functional significance in glioma remains incompletely understood." (PMID 41423530, 2025). "Notably, high CAPS expression was associated with favorable prognosis in UCEC (HR = 0.46,95% CI: 0.29-0.72, P < 0.001), but correlated with poor survival outcomes in lower-grade glioma (LGG) (HR = 2.39, 95% CI: 1.69-3.38, P < 0.001)." (PMID 41383604, 2025).
lung carcinoma (3 papers, 2025). "CAPS is recognized as a possible prognostic indicator in various human carcinomas, including lung cancer." (PMID 39994841, 2025).
breast carcinoma (2 papers, 2015 to 2022). "Validation of the highest expressed protein in the relapse group, CAPS, in the whole cohort implicate CAPS as a potential predictive factor in ER positive breast cancer receiving adjuvant tamoxifen." (PMID 25878567, 2015). "High levels of CAPS were statistically significantly correlated to lower RFS both in uni- and multivariate analyses, including important breast cancer prognostic markers as nodal status, tumor size, age and ER and PgR levels." (PMID 25878567, 2015).
ovarian carcinoma (2 papers, 2020 to 2025). A malignant neoplasm originating from the surface ovarian epithelium. "Specifically, elevated CAPS expression was detected in 11 cancer types, including uterine corpus endometrial carcinoma (UCEC), breast invasive carcinoma (BRCA), and ovarian cancer (OV)." (PMID 41383604, 2025).
serous carcinoma (2 papers, 2022 to 2025). "In contrast, CAPS expression was markedly reduced in high-grade tumors (G2-G3), serous carcinoma, advanced-stage disease (stage III-IV), and tumors with deep myometrial invasion (all P < 0.05)." (PMID 41383604, 2025). "Both FOXJ1 and CAPS expression levels differed markedly between serous borderline tumors and serous carcinomas." (PMID 36552773, 2022). "The average percentage of CAPS+ cells decreased with increasing tumor grade (40% in benign serous cystadenomas, 31.54% in serous borderline tumors, 18.86% in low-grade serous carcinomas, and 2.7% in HGSOCs." (PMID 36552773, 2022). "Similarly, the mean CAPS expression in serous borderline serous tumors was 9.508 compared to 8.207 in serous carcinomas (p = 3.09 × 10−27)." (PMID 36552773, 2022).
type II diabetes (2 papers, 2017 to 2020). "While some of these illnesses are caused by mutations in inflammasome components (e.g., CAPS, FMF), others are due to indirect effects on inflammasome activation (e.g., PAPA, gout, type II diabetes)." (PMID 31936823, 2020).
autoimmune disease (1 paper, 2019). A disorder resulting from loss of function or tissue destruction of an organ or multiple organs, arising from humoral or cellular immune responses of the individual to their own tissue constituents. "Interestingly some low penetrance NLRP3 CAPS mutations have been described in patients diagnosed with MS, suggesting a role for the inflammasome in the onset of autoimmune diseases." (PMID 31170158, 2019).
bladder carcinoma (1 paper, 2025). "Importantly, pan-cancer analyses in additional tumor types, including bladder carcinoma (BLCA), clear cell renal cell carcinoma (KIRC), and colorectal adenocarcinoma (COAD), consistently demonstrated correlations between CAPS expression and immune microenvironment remodeling." (PMID 41383604, 2025).
breast tumor (1 paper, 2015). "Based on this small verification we performed protein quantification by ELISA for CAPS and MX1 on 79 and 89 breast tumor homogenates respectively." (PMID 25878567, 2015).
colon cancers (1 paper, 2025). "CAPS expression was positively correlated with TMB in glioblastoma but negatively correlated in gastric and colon cancers." (PMID 41383604, 2025).
congestive heart failure (1 paper, 2022). Failure of the heart to pump a sufficient amount of blood to meet the needs of the body tissues, resulting in tissue congestion and edema. "Given that AECOPD patients with higher CAPS levels might have a higher risk of congestive heart failure, there might be a correlation between CAPS and congestive heart failure." (PMID 35509893, 2022).
cystadenoma (1 paper, 2022). A benign or borderline cystic epithelial neoplasm arising from the glandular epithelium. "Among 39 mucinous tumors (9 benign, 12 borderline, 5 low-grade carcinomas, and 13 high-grade carcinomas), only one benign cystadenoma (11.11%) and one high-grade carcinoma (7.69%) had CAPS+ cells." (PMID 36552773, 2022). "Interestingly, the average percentage of CAPS+ cells for all cases decreased with increasing grade aggressiveness of serous lesions (~40% in cystadenomas, ~30% in borderline tumors, ~20% in low-grade carcinomas, and <3% in HGSOCs." (PMID 36552773, 2022).
endometrioid carcinomas (1 paper, 2022). "In endometrioid carcinomas, CAPS+ cells were present in 8 of 9 (88.88%) low-grade and 9 of 29 (31.03%) high-grade carcinomas." (PMID 36552773, 2022). "The average percentage of CAPS+ cells for all cases was markedly different between low-grade and high-grade endometrioid carcinomas (43.33% vs. 4.31%)." (PMID 36552773, 2022).
endometrioid endometrial carcinoma (1 paper, 2025). "CAPS was significantly upregulated in early-stage, low-grade, and endometrioid endometrial carcinoma, and its elevated expression was associated with improved patient survival." (PMID 41383604, 2025).
gynecological cancer (1 paper, 2020). "In analyzing potential links between STIC and EIC cells and their respective invasive carcinomas, two of the identified proteins were of particular interest based on their involvement in gynecological cancer development: Epithelial cell adhesion molecule (EPCAM) and Calcyphosin (CAPS)." (PMID 33384952, 2020).
Hydrocephalus (1 paper, 2026). Hydrocephalus is an active distension of the ventricular system of the brain resulting from inadequate passage of CSF from its point of production within the cerebral ventricles to its point of absorption into the systemic circulation. "CAPS and FSTL1 may represent exploratory proteins of interest within different hydrocephalus-related annotation contexts." (PMID 42293101, 2026).
Majeed syndrome (1 paper, 2022). Majeed syndrome is a rare genetic multisystemic disorder characterized by the triad of chronic recurrent multifocal osteomyelitis, congenital dyserythropoietic anemia, and variable transient inflammatory dermatosis. "Monogenic SAIDs mediated by IL-1 include MKD, FMF, TRAPS, PAAND, PAPA, CAPS, DIRA, Majeed syndrome, NAIAD, NLRC4-MAS, PFIT, APLAID." (PMID 36253853, 2022).
metastatic tumors (1 paper, 2022). "Using the “HGSOC Progression” TMA, we compared the percentage of 42 patient-matched primary, synchronous metastatic, and metachronous/recurrent metastatic tumors for the presence of FOXJ1+ and/or CAPS+ cells." (PMID 36552773, 2022).
mucinous carcinomas (1 paper, 2022). "Overall, CAPS+ cells were observed in 45% of the serous, 45% of the endometrioid, and 30% of clear cell compared to only 6% of mucinous carcinomas (p = 0.01)." (PMID 36552773, 2022).
mucinous tumors (1 paper, 2022). "Most mucinous tumors expressed relatively low mRNA levels of ciliated cell markers FOXJ1 and CAPS and there was a clear dichotomy in PAX8 mRNA expression when mucinous EOC were compared to serous, endometrioid, and clear cell EOC." (PMID 36552773, 2022). "Of note, mucinous tumors expressed low levels of both ciliated cell (FOXJ1, CAPS) and secretory cell (PAX8) cell markers, possibly suggesting a different cell of origin for this histologic subtype." (PMID 36552773, 2022).
nasopharyngeal carcinoma (1 paper, 2021). A carcinoma arising from the nasopharyngeal epithelium. "In addition, consistent with the expression of CAPS and WFDC2 in nasopharyngeal carcinoma, Kaplan Meier’s survival analysis exhibited the remarkable prolongation of the overall survival periods in the patients with low CAPS and WFDC2." (PMID 33790390, 2021).
ovarian cystadenoma (1 paper, 2022). A benign ovarian surface epithelial-stromal tumor characterized by the presence of cystic structures lined by serous epithelial cells, mucinous columnar epithelial cells, or endometrial-type well-differentiated cells. "In ovarian cystadenomas, borderline tumors, and low-grade carcinomas, CAPS+ cells were typically associated with easily recognized cilia while cilia were rarely recognizable in high-grade carcinomas." (PMID 36552773, 2022).
serous cystadenoma (1 paper, 2022). A serous neoplasm in which the cysts and papillae are lined by a single layer of cells without atypia, architectural complexity or invasion. "While CAPS+ cells were detected in approximately 85% of serous cystadenomas, borderline tumors, and low-grade carcinomas, they were detected in <40% of HGSOCs." (PMID 36552773, 2022). "Additionally, we found that the presence of CAPS+ cells is not limited to low-grade serous EOC as we detected CAPS+ cells in approximately 85% of serous cystadenomas, borderline tumors, and low-grade carcinomas compare to <40% of HGSOC." (PMID 36552773, 2022).
uterine sarcoma (1 paper, 2025). "Pan-cancer genomic analyses revealed that CAPS transcription is primarily regulated by copy number variation, with frequent deep deletions observed in UCEC and uterine sarcoma." (PMID 41383604, 2025).
cancer (10 papers, 2020 to 2026). A tumor composed of atypical neoplastic, often pleomorphic cells that invade other tissues. "Selective recognition of cancer-associated proteins (CAPs) by antibodies, followed by their delivery into the intracellular organelle, the lysosome, results in targeted degradation of CAPs and suppresses the growth of cancer cells." (PMID 41738074, 2026). "In this study, we employed an integrative multi-omics approach, including pan-cancer genomic profiling and single-cell transcriptomic analysis, to comprehensively characterize the molecular and functional roles of CAPS in EC." (PMID 41383604, 2025). "Increasing evidence indicates aberrant CAPS expression across multiple cancers, implicating it in oncogenic signaling." (PMID 41383604, 2025). "Given its pronounced upregulation and emerging relevance in cancer biology, CAPS was selected for further mechanistic study." (PMID 41423530, 2025). "Although its functions are not yet properly uncovered, CAPS has been extensively studied in the last decades in the context of numerous diseases, among which several types of carcinomas, observing changes in CAPS level." (PMID 40729375, 2025). "mRNA data from an independent cohort showed higher FOXJ1 and CAPS expression in serous borderline tumors and low-grade carcinomas compared to HGSOC." (PMID 36552773, 2022). "CAPS+ cells were observed in normal fallopian tubes and endometria and in ~85% of serous benign and borderline tumors and low-grade carcinomas but only in <40% of HGSOC." (PMID 36552773, 2022). "Moreover, CAPS seems to play a role in stimulating the proliferation of cancer cells through the modulation of the cited pathways in which CAPS is involved or downregulating cell differentiation following the stimulus of the epidermal growth factor." (PMID 40729375, 2025). "Furthermore, compared to healthy cells, cancer cells usually have higher membrane fluidity, resulting in easier membrane destabilization by membrane-bound CAPs." (PMID 40076518, 2025). "Calcyphosine (CAPS) is an EF-hand Ca2+-binding phosphoprotein originally identified as a cAMP-dependent substrate in thyroid tissue; recent studies have drawn attention to its relevance in cancer biology." (PMID 41383604, 2025). "First, we used the SingleR package and the known markers of cancer and alveolar cells to identify a cancer cluster and alveolar cluster; EPCAM and SOX4 were used to mark the cancer cluster; SFTPC and SFTPA1 to mark the alveolar cluster; CAPS and TPPP3 to mark epithelial cells." (PMID 33783985, 2021). "Interestingly, for the CAPS gene, we do observe a difference in mean expression of the gene between cancer tissues and control whereas no differential expression was detected at individual level." (PMID 32392248, 2020).